PALB2 (partner and localizer of BRCA2)
Description:
Plays a critical role in homologous recombination repair (HRR) through its ability to recruit BRCA2 and RAD51 to DNA breaks. Strongly stimulates the DNA strand-invasion activity of RAD51, stabilizes the nucleoprotein filament against a disruptive BRC3-BRC4 polypeptide and helps RAD51 to overcome the suppressive effect of replication protein A (RPA). Functionally cooperates with RAD51AP1 in promoting of D-loop formation by RAD51. Serves as the molecular scaffold in the formation of the BRCA1-PALB2-BRCA2 complex which is essential for homologous recombination. Via its WD repeats is proposed to scaffold a HR complex containing RAD51C and BRCA2 which is thought to play a role in HR-mediated DNA repair. Essential partner of BRCA2 that promotes the localization and stability of BRCA2. Also enables its recombinational repair and checkpoint functions of BRCA2. May act by promoting stable association of BRCA2 with nuclear structures, allowing BRCA2 to escape the effects of proteasome-mediated degradation. Binds DNA with high affinity for D loop, which comprises single-stranded, double-stranded and branched DNA structures. May play a role in the extension step after strand invasion at replication-dependent DNA double-strand breaks; together with BRCA2 is involved in both POLH localization at collapsed replication forks and DNA polymerization activity.
Synonyms: FANCN; FLJ21816; BROVCA5; PNCA3
Tractability: Small molecule: it has a high-quality binding pocket. PROTAC: ubiquitination databases record sites on it.
Gene: Protein-coding gene on chromosome 16 (23,603,160 to 23,641,321, reverse strand). Ensembl gene ENSG00000083093.
Subcellular location: Nucleus
Subcellular location (Human Protein Atlas): Nuclear speckles; Nucleoplasm
Pathways (Reactome):
DNA Repair: HDR through Homologous Recombination (HRR); Homologous DNA Pairing and Strand Exchange; Resolution of D-loop Structures through Holliday Junction Intermediates; Resolution of D-loop Structures through Synthesis-Dependent Strand Annealing (SDSA)
Disease: Defective HDR through Homologous Recombination Repair (HRR) due to PALB2 loss of BRCA1 binding function; Defective HDR through Homologous Recombination Repair (HRR) due to PALB2 loss of BRCA2/RAD51/RAD51C binding function; Defective homologous recombination repair (HRR) due to BRCA1 loss of function; Impaired BRCA2 binding to PALB2
Cellular responses to stimuli: KEAP1-NFE2L2 pathway
Metabolism of proteins: Neddylation
Gene Ontology:
Molecular function: DNA binding; protein binding
Biological process: double-strand break repair via homologous recombination
Cellular component: DNA repair complex; nuclear speck; nucleoplasm; nucleus; protein-containing complex
Genetic constraint (gnomAD): Loss-of-function variants: 77 observed, 103.47 expected, observed/expected ratio (o/e) 0.74, 90% interval 0.62 to 0.9. The upper end of that interval is the gene's LOEUF score, 0.9, which puts it in group 3 of 6, group 1 being the genes least tolerant of losing a copy. Missense variants: 1,340 observed, 1,424.8 expected, observed/expected ratio (o/e) 0.94, 90% interval 0.9 to 0.98. Synonymous variants: 481 observed, 517.42 expected, observed/expected ratio (o/e) 0.93, 90% interval 0.86 to 1.
Gene-disease validity (ClinGen):
ClinGen rates the evidence that PALB2 causes each of these diseases.
Fanconi anemia complementation group N (autosomal recessive): Definitive. Any Fanconi anemia in which the cause of the disease is a mutation in the PALB2 gene.
PALB2-related cancer predisposition (autosomal dominant): Definitive. Hereditary cancer predisposition due to variation(s) in the PALB2 gene.
Homologues: Orthologues: chimpanzee PALB2 (99% identical), macaque PALB2 (91% identical), dog PALB2 (72% identical), rabbit PALB2 (69% identical), guinea pig PALB2 (68% identical), pig PALB2 (66% identical), rat Palb2 (59% identical), mouse Palb2 (59% identical), tropical clawed frog palb2 (28% identical), zebrafish palb2 (9% identical).
Diseases named in the same sentence as PALB2 in open-access papers:
PALB2 is named in the same sentence as 194 diseases in open-access papers, as found by Europe PMC text mining. Sharing a sentence is not in itself a finding about the gene and the disease. The quoted sentences say what the papers report.
breast cancer (635 papers, 2007 to 2026). A primary or metastatic malignant neoplasm involving the breast. "In women carrying a pathogenic PALB2 variant, the risk of developing breast cancer by age 80 is approximately 53%, while the risk for ovarian cancer stands at circa 5%." (PMID 41528496, 2026). "PALB2 mutations also confer substantial risk, with carriers having a 35% probability of developing breast cancer by the age of 70 years." (PMID 41510186, 2026). "For example, the estimated absolute lifetime risk of breast cancer associated with PALB2 variants is about 40%: a high frequency that approaches the risk of breast cancer in individuals with BRCA2 variants." (PMID 39831988, 2025). "These pleiotropic effects point to the potential of IQGAP1 as both a biomarker and a therapeutic target in PALB2-mutated breast cancers." (PMID 40868059, 2025). "Our results suggest a 55–80% likelihood of receiving chemotherapy for BRCA1/2 breast cancer and provide early estimates for patients with PALB2-associated disease." (PMID 40275390, 2025). "We observed modest evidence of reduced breast cancer risk associated with breastfeeding for carriers of PVs in PALB2 (OR = 0.08; 95% CI, 0.00–0.92; P value = 0.042)." (PMID 40298171, 2025). "While mutations in the PALB2 gene have been associated with an increased risk of breast cancer in males, its role in other cancers, including AC, remains poorly understood." (PMID 40963972, 2025). "The second most upregulated gene, partner and localizer BRCA2 (PALB2; >3.1-fold), is involved in DNA damage repair, and its mutation is associated with increased risk of male breast cancers." (PMID 41205594, 2025). "Of these, one individual was found to carry a variant in BRCA2 (NM_000059.3), and another one carried a variant in PALB2 (NM_024675.3); both genes being associated with increased risk for breast cancer." (PMID 40679974, 2025). "The study aims to include women carrying a germline P/LP variant (BRCA1, BRCA2, or PALB2), or >5% Tyrer–Cuzick breast cancer risk at ten years, or with a previous diagnosis with intraepithelial neoplasia within the last three years." (PMID 39858629, 2025). "Mutations in either BRCA2 or PALB2 reduce the HR repair capacity, thereby increasing the risk of breast cancer and potentially prime for cardiotoxic events." (PMID 39621070, 2025). "We retrospectively reviewed treatment administered following a first diagnosis of BRCA1/2- and PALB2-associated breast cancer between 2002 and 2022." (PMID 40275390, 2025). "Pre-diagnostic awareness of a germline pathogenic variant in BRCA1/2 or PALB2 allows for enhanced screening and risk-reducing mastectomy, the latter of which dramatically lowers the likelihood of being diagnosed with breast cancer." (PMID 40275390, 2025). "For females ≥18 years with a GPV in BRCA1, BRCA2 or PALB2, a referral to the very high-risk breast cancer screening (VHRS) programme or equivalent should be made at the time of diagnosis." (PMID 41159931, 2025). "Oncogenic dominant variants were observed in 4.2% of our cohort, of whom 2 individuals presented with P variants in BRCA2 and PALB2, both being linked to breast cancer and accounting together for 0.4% of our cohort." (PMID 40679974, 2025). "PALB2 c.3122A>C p.(Lys1041Thr): This variant has been previously observed in breast cancer and pediatric acute myeloid leukemia, though functional studies suggest limited impact." (PMID 41294693, 2025). "The Multiplex Taqman assay for the rs80359550 (BRCA2) and rs180177102 (PALB2) variants has shown a strong correlation with breast cancer risk." (PMID 40158114, 2025). "PALB2 is a highly important protein in the HR pathway, and is closely associated with the occurrence of breast cancer and the sensitivity of PARPi treatment." (PMID 40830526, 2025). "A biallelic mutation in PALB2 can cause Fanconi anemia, and monoallelic mutations can increase susceptibility to breast cancer, ovarian cancer, and pancreatic cancer." (PMID 39745016, 2025).
breast cancer (continued). "PALB2 mutation carriers have an increased risk of breast cancer (men and women), prostate cancer, ovarian cancer, pancreatic cancer, and some other types of carcinomas." (PMID 40564049, 2025). "The available literature also suggests that PALB2-associated breast cancers are biologically aggressive, with TNBC diagnosed in approximately one third of breast cancer cases." (PMID 40275390, 2025). "In PTV meta-analyses including FinnGen10, the BRCA2 association was attenuated, but CHEK2 and PALB2 were more strongly associated with breast cancer." (PMID 41044259, 2025). "Key consensus points established specific age-based recontact practices for high penetrance CSGs, BRCA1, BRCA2 and PALB2, including recontact at 25 years to review breast cancer risk management and ovarian cancer risk management at gene-specific ages." (PMID 41159931, 2025). "For PALB2 P/LP variant carriers, the surveillance for breast cancer should be equivalent to that for BRCA1 and BRCA2 P/LP variant carriers." (PMID 39858629, 2025). "Although PALB2 mutations are primarily associated with an increased risk of other cancers, such as breast cancer, recent studies have examined their potential role in hereditary colorectal cancer." (PMID 40869938, 2025). "The risk associated with breast cancer for P/LP variants in PALB2 varied between moderate and high (OR 3.83–5.02), whereas those in CHEK2 and ATM were associated with moderate risk (OR 2.54–2.47 and OR 1.82–2.10, respectively)." (PMID 39858629, 2025). "The biologic differences between BRCA1 and BRCA2-associated breast cancers have been well established in the literature, with data on PALB2 continuing to evolve." (PMID 40275390, 2025). "HRDsig positivity has been reported in 82% of germline or somatic g/sBRCA1/BRCA2 or germline PALB2-mutated breast cancers and 16.5% of HRR wild-type cancers." (PMID 40864792, 2025). "Of 895 patients with a known pathogenic variant in BRCA1/2 and PALB2 or other breast cancer susceptibility genes, we identified 312 affected female BRCA1/2 and PALB2-positive patients with breast cancer." (PMID 40275390, 2025). "The Breast Cancer Association Consortium also reported a moderate risk of 2.5 for DCIS in association with PALB2 mutations." (PMID 40770660, 2025). "A retrospective study conducted on a Chinese pan-cancer patient cohort revealed the presence of reversion mutations in three HRR-associated genes: BRCA1, BRCA2, and PALB2, across breast cancer, pancreatic cancer, OC, and lung cancer." (PMID 40166687, 2025). "Chemotherapy receipt varied significantly by pathogenic variant and age at diagnosis, with BRCA1 carriers, PALB2 carriers, and early-onset breast cancers diagnosed under 30 years of age receiving chemotherapy in greater than 80% of cases." (PMID 40275390, 2025). "Disease-causing mutations that cause loss of PALB2 function have been found in populations in many countries, with detection rates of 0.6–3.9% in individuals with a family history of breast cancer." (PMID 38439896, 2024). "Two patients with PALB2 pathogenic variants had positive family histories: one with a history of breast cancer in her mother, and the other with a history of breast cancer in her aunt." (PMID 38914840, 2024). "Precision medicine and personalized risk assessment for PALB2 mutation-associated breast cancer are now achievable, but further clinical trials are needed to validate the efficiency of targeting this gene for a therapeutic approach." (PMID 39274207, 2024). "Given the distinct classification of histological subtypes of breast cancer, only a limited number of studies have documented the risk associated with PALB2 mutations in invasive micropapillary carcinoma of the breast." (PMID 38914840, 2024).
breast cancer (continued). "Instead, monoallelic PALB2 PVs can be found in 0.4% to 3.9% of breast cancer patients and have been linked to a 41–60% risk of breast cancer, a 3–5% risk of ovarian cancer, and 2–5% risk of pancreatic cancer." (PMID 39682206, 2024). "Heterozygous mutations in any of three major genes, BRCA1, BRCA2 and PALB2, are associated with high-risk hereditary breast cancer susceptibility frequently seen as familial disease clustering." (PMID 38597967, 2024). "In further study, we would included MLPA testing to obtain a more comprehensive understanding of the PALB2 mutation spectrum in Chinese patients with early-onset breast cancer." (PMID 38914840, 2024). "In affected PALB2 carriers who are premenopausal at diagnosis, a recent report found 10-year contralateral breast cancer risk to be 12.2%, increasing to 35.5% in those with ER disease." (PMID 38248108, 2024). "In this study, we identified 12 carriers of PALB2 pathogenic variants in 1556 Chinese patients with BRCA1/2-negative early-onset breast cancer, resulting in a mutation frequency of 0.77%." (PMID 38914840, 2024). "The estimated lifetime risk of breast cancer for female carriers of PALB2 variants is 53% by age 80 (95% confidence interval, 44–63%)." (PMID 39409938, 2024). "The prevalence of the germline PALB2 pathogenic variants was approximately 0.77% in Chinese patients with BRCA1/2-negative early-onset breast cancer." (PMID 38914840, 2024). "PALB2 is considered the third most significant breast cancer susceptibility gene after BRCA1/2 due to its penetrance and prevalence." (PMID 39684258, 2024). "Patients with HER2-/HR+ breast cancer exhibited the highest PALB2 pathogenic variant prevalence at 1.08% (9/833), constituting 75.0% (9/12) of all PALB2 carriers." (PMID 38914840, 2024). "A PALB2-variant breast cancer is usually associated with an aggressive clinicopathological features and is often of triple-negative phenotype." (PMID 38817905, 2024). "Analysis of the genetics in a large-scale early-onset breast cancer cohort will offer a deeper insight into the distribution and characteristics of PALB2 variants within this group." (PMID 38914840, 2024). "One child had positive secondary findings (PALB2), which is associated with an increased susceptibility to breast cancer." (PMID 39678379, 2024). "For example, WGS revealed a breast-cancer-predisposing germline variant (frameshift variant in PALB2) in a girl with a thoracic neuroblastoma (CUH_0016)." (PMID 38956197, 2024). "Several studies have demonstrated that ATM and PALB2 mutations confer a moderate risk of developing breast cancer." (PMID 39640102, 2024). "Given the diverse spectrum of PALB2 variants across ethnicities and regions, it is crucial to investigate the spectrum of PALB2 variants in Chinese patients with early-onset breast cancer." (PMID 38914840, 2024). "Individuals with pathogenic PALB2 variants are advised to follow breast cancer risk management protocols similar to those for individuals with BRCA1/2 variants." (PMID 39409938, 2024). "In carriers of the pathogenic variant in the PALB2 gene, a lifetime risk for the development of breast cancer is 40%–60%, for ovarian cancer 3%–5%, and for pancreatic cancer 2%–3%." (PMID 38817905, 2024). "Biallelic modifications in PALB2, also known as FANCN, led to a distinct type of Fanconi anemia, while monoallelic PALB2 variants are linked to breast cancer and ovarian cancer with a 41–60% and 3–5% absolute risk, respectively." (PMID 38397209, 2024). "Germline PALB2 variants are associated with a moderate-to-high risk of development breast cancer, specifically in younger carriers." (PMID 38914840, 2024). "PVs in genes with moderate penetrance, such as ATM, CHEK2, BRIP1, and PALB2, double the risk of breast cancer." (PMID 39624521, 2024).
breast cancer (continued). "Germline pathogenic variants (PVs) in ATM, BRCA1, BRCA2, CHEK2, and PALB2 are detected in 5-7% of unselected women with breast cancer in the general population and are associated with a significantly increased risk of breast cancer in unaffected women." (PMID 39624521, 2024). "Heterozygous germline pathogenic variants of PALB2 significantly increase the lifetime risk of breast cancer and moderately increase the risk of ovarian and pancreatic cancers." (PMID 39409938, 2024). "The prevalence of germline PALB2 pathogenic variants has been identified in 0.66–0.97% of Chinese patients with breast cancer unselected for predisposing factors, 0.40%–0.86% in other Asian cohorts (Japan and Malaysia), and 0.87% in Caucasian population." (PMID 38914840, 2024). "Based on its mutation frequency and disease penetrance, PALB2 is considered as the third major high-risk breast cancer gene alongside BRCA1 and BRCA2, all of which being key factors for the maintenance of genome stability." (PMID 38597967, 2024). "PALB2 pathogenic variants are reported to be significantly associated with TNBC or HR-negative breast cancer in the unselected breast cancer cohorts." (PMID 38914840, 2024). "BC that is linked withgerminal mutations in BRCA1 has a triple negative phenotype(70–85 %), while ER-positive cases can be detected in carriersof mutations in the BRCA2, ATM, CHEK2 and PALB2 genes." (PMID 39027127, 2024). "To validate our preclinical findings, we performed pFLT1 and FLT1 immunostaining on tissue specimens that were obtained prior to PARPi treatment from 10 breast cancer patients harboring mutations in the BRCA1/2 or PALB2 DNA damage response (DDR) genes." (PMID 38956205, 2024). "CPM decisions are also frequently observed in patients with ATM, CHEK2, and PALB2, which are the three most common moderate-risk breast cancer genes." (PMID 39335183, 2024). "Pathogenic variants in the breast cancer susceptibility gene PALB2 are associated with an approximate 53% (95% CI 44–63%) lifetime risk of developing breast cancer, increasing to 68% in those with multiple affected first-degree relatives." (PMID 38248108, 2024). "The prevalence of germline pathogenic variants in PALB2 among breast cancer patients has been reported to range from approximately 0.23–2.65%." (PMID 39409938, 2024). "Individuals aged over 40 years carrying the PALB2 gene exhibit a 5–8 times higher risk of breast cancer compared to the general population, whereas PALB2 carriers aged below 40 years exhibit an 8–9 times higher risk than the general population." (PMID 38914840, 2024). "In contrast, heterozygous germline pathogenic variants in PALB2 significantly increase the lifetime risk of breast cancer and moderately increase the risks of ovarian and pancreatic cancers." (PMID 39409938, 2024). "Pathogenic PALB2 germline variants frequently predispose their female carriers to breast carcinoma with a high disease penetrance." (PMID 38597967, 2024). "Association with overall breast cancer is also depicted for PTVs in PALB2 with adjusted ORs of 16.14 (0.85-305.14 95% CI, p-value = 0.064), although not statistically significant." (PMID 37790698, 2023). "Based on our results, in Poland, we use a panel of founder mutations in BRCA1, BRCA2, CHEK2, and PALB2 as an initial screening tool for all patients with breast cancer and unaffected individuals with a positive family history of breast cancer." (PMID 37510234, 2023). "Still, for genetic counselors, it has to be considered that germline PALB2 P/LP variants were also reported in males in other studies and that it represents an increased risk for developing male breast cancer (odds ratio, OR = 6.6)." (PMID 37686625, 2023). "Our study depicted the mutational patterns of BRCA1, BRCA2, and PALB2 in Taiwanese breast cancer patients through tumor-only sequencing." (PMID 38098088, 2023).